IL6 (interleukin 6)
Diseases named in the same sentence as IL6 in open-access papers (continued):
Sharing a sentence is not in itself a finding about the gene and the disease.
glioma (continued). "The pooled HR was 1.10 (95% CI: 1.05‐1.16; P = .000), indicating that an elevated circulating IL‐6 level predicted poor OS in glioma patients." (PMID 31599129, 2019). "IL-1β, IL-6, TGF-β, and EGF have been shown to promote glioma invasion from tumor-associated macrophage secretion." (PMID 31300060, 2019). "Elevated expression of IL-6 is inversely correlated with the survival time of glioma patients, and IL-6 is involved in glioma growth, angiogenesis, and resistance to chemotherapy, radiation, and apoptosis." (PMID 32117213, 2019). "One of these gene targets is Socs3, which has been shown to be repressed by miR-30 in glioma stem cells and is induced by Interleukin-6 (IL6; Shuai and Liu, 2003)." (PMID 31440139, 2019). "More recently, IL-6 was shown to induce glioma stem cell (GSC) expansion via STAT3 signaling, as measured by CD133 expression, and implied by neurosphere formation, and enhanced growth of intracranial xenografts." (PMID 31361777, 2019). "The pooled SMD was 0.81 (95% CI: 0.21‐1.40; P = .008), indicating that the level of IL‐6 in the peripheral blood of glioma patients was significantly higher than that of the normal control group." (PMID 31599129, 2019). "The results showed that increased circulating IL‐6, IL‐8, IL‐17, TNF‐α, TGF‐β, and CRP levels before treatment are significantly associated with glioma risk." (PMID 31599129, 2019). "On the other hand, our results showed a poor prognostic outcome in glioma patients expressing high levels of circulating IL‐6 and CRP." (PMID 31599129, 2019). "AP-2α functions as a novel tumor suppressor to inhibit the stemness of glioma cancer cells by inhibiting the Nanog/Sox2/CD133 regulatory axis and decreasing the resistance of glioma cells to TMZ by blocking the IL6/Jak2/STAT3 signaling pathway." (PMID 31534499, 2019). "In orthotopic murine glioma models, the inhibition of IL-6 signaling led to reduced myeloid PD-L1 expression, diminished tumor growth, and increased survival." (PMID 31192256, 2019). "Our results indicate that increased circulating IL‐6, IL‐8, IL‐17, TNF‐α, TGF‐β, and CRP levels are significantly associated with increased glioma risk." (PMID 31599129, 2019). "The most important cytokines secreted by gliomas after irradiation were interleukins (IL-6, IL-8) and several growth factors (TGF-ß, VEGF)." (PMID 30463322, 2018). "Specifically, the glioma growth is induced by the IL-6 levels, which are produced by microglial cells under stimulation of glioma-released CCL2 that acts upon CCR2 in microglia." (PMID 30123112, 2018). "TGF-β1 induces cancer stem cell-like properties in HCC and glioma.IL-8 and IL-6 enhance the invasion of LoVo cells." (PMID 29338742, 2018). "Here we identify IL-6 as a major driver for alternative macrophage activation in glioma microenvironment." (PMID 29422647, 2018). "Glioma-associated MSCs increased the proliferation and self-renewal of glioma stem cells in vitro and enhanced their tumorigenicity and mesenchymal features in vivo through the IL-6/gp130/STAT3 pathway activation." (PMID 30310111, 2018). "Recent evidence reported that cAMP/PKA enhances IL-1β induced-IL-6 synthesis through Jak2/Stat3 activation, identifying novel therapeutic targets for the treatment of glioma." (PMID 28157712, 2017). "IL-6 signaling is essential for the proliferation, differentiation, aggressiveness, and migration of glioma cells." (PMID 28881826, 2017). "In this report, we preliminarily explore a correlation of VM with TAMs in human glioma tissues, and the regulatory mechanisms how M2-like macrophages promote VM through amplifying IL-6 secretion in glioma cells." (PMID 27903982, 2017). "NFAT1-regulated IL6 signalling contributes to aggressive phenotypes of gliomas, emphasizing the role of immunomodulatory factors in glioma malignant progression." (PMID 29258522, 2017).
glioma (continued). "Another study found a compelling correlation between IL-6 mRNA level and extent of glioma malignancy; this study also demonstrated a significant inhibition of brain tumor development upon inhibition of IL-6 signaling." (PMID 28346397, 2017). "High IL6- and IL6R-expression were significantly associated with mesenchymal subtype and IDH-wildtype gliomas, and were predictors of poor survival." (PMID 29258522, 2017). "Firstly, we examined the effect of IL6 stimulation on glioma cell proliferation and apoptosis by treating M1 and U87 cells with different concentrations of IL6." (PMID 29258522, 2017). "Another outcome of hypoxia in glioma cells was the stimulation of IL6 production and cytokine-mediated autophagy activation." (PMID 28459042, 2017). "Taken together, monocyte-derived M2 macrophages also induced VM promotion via IL-6 amplification in glioma cells." (PMID 27903982, 2017). "Compared to THP-1-CM-treated group, transcription and secretion of IL-6 in glioma cells were markedly increased by M2-CM in dose-dependent manner." (PMID 27903982, 2017). "Increased expression of IL-1β, IL-6, and IL-8 was also observed in glioma patient samples and was correlated with cancer invasiveness and survival of patients." (PMID 28881826, 2017). "All together, these data showed that hypoxia-induced IL-6 secretion increases lncTCF7 expression, which is important for the migration and proliferation of glioma cells." (PMID 29234033, 2017). "The in vitro studies suggested that M2-like macrophages and monocyte-derived M2 macrophages drove VM formation through upregulating IL-6 expression in glioma cells via PKC pathway." (PMID 27903982, 2017). "Specifically, IL-6 is heavily involved in glioma development through the promotion of angiogenesis, cell proliferation and resistance to apoptosis and radiation." (PMID 28107450, 2017). "Our results showed that the binding of STAT3 to the lncTCF7 promoter region was similar in both glioma cell lines, especially with the IL-6 (20 ng/ml) stimulus." (PMID 29234033, 2017). "A pharmaceutical monoclonal anti-IL-6 antibody inhibited glioma cell proliferation, radiation induced increased IL-6 synthesis (cf Section 2.c." (PMID 28977822, 2017). "IL6 signalling mediated by NFAT1 contributes to aggressive phenotypes of gliomas, which suggests an important role of immunomodulatory factors in glioma malignant progression." (PMID 29258522, 2017). "Blocking of IL6, hence autophagy inhibition, by antibody drugs alone or in combination with temozolomide (a first-line drug for glioma treatment) decreased cancer cell survival and the tumor burden." (PMID 28459042, 2017). "IL-6 production by glioma cells was dramatically increased in the medium of monocyte-derived M2-CM/glioma coculture system, compared to other groups." (PMID 27903982, 2017). "The M2-CM facilitated the IL-6 production and VM formation of glioma cells via PKC pathway compared to THP-1-CM, and the facilitation was mostly abrogated by inhibition of PKC signaling." (PMID 27903982, 2017). "Taken together, our results suggested that M2-like macrophages drove glioma VM through amplifying IL-6 secretion in glioma cells via PKC pathway." (PMID 27903982, 2017). "In view of the complexity of the PKC pathway, the specific mechanisms which M2-CM promoted IL-6 expression and VM formation in glioma cells need further investigation by isoform-specific inhibitors." (PMID 27903982, 2017). "It was reported that IL-6 secreted by glioma cells enhances the invasive potential of these cells and that IL-8 is important for glial tumour neovascularity and progression." (PMID 28598356, 2017). "Glioma cells produce various inflammatory mediators, such as IL-1β, IL-6, IL-8, IL-10, MCP-1, and MIP." (PMID 28881826, 2017). "Previous studies determined that IL6 signalling in gliomas acted as a key regulator of the immunosuppressive microenvironment and was an important promoter of proliferation, survival and invasiveness of tumour cells." (PMID 29258522, 2017).
glioma (continued). "Upregulated IL-6 production in microglia stimulates glioma invasiveness, and it was suggested that the CCL2/CCR2/IL-6 loop represents a potential target to interfere with glioma invasion." (PMID 29258556, 2017). "Due to its indispensable role in glioma development, IL-6 is a promising target for immunotherapy in GBM treatment." (PMID 28346397, 2017). "One such factor is the pleiotropic cytokine, interleukin-6 (IL-6); a potent mediator that is omnipresent in the inflammatory microenvironment of most solid tumors, including glioma." (PMID 27903982, 2017). "For example, interleukin 6 (IL-6)/IL-6 receptor (IL-6R)-mediated signaling pathways are involved in the regulation of EMT in glioma cells." (PMID 27524415, 2017). "The expression of IL6, p-STAT3, HIF1A, and LC3B positively correlated with the WHO grade of glioma, and Pearson's or Spearman's rho rank correlation tests showed that IL6, p-STAT3, HIF1A, LC3B and grade were positively correlated." (PMID 27163161, 2016). "MMP14 protein levels were nearly completely abolished in glioma cells in the presence of IL-6 antibodies." (PMID 27613828, 2016). "Of note, STAT3 is also the downstream signaling pathway of another crucial CSCs regulator IL-6 in glioma and colon CSCs." (PMID 27738346, 2016). "Although IL-6 has been traditionally considered to be secreted by glioma cells, the source of IL-6 in glioma specimens still remains a controversial issue." (PMID 27613828, 2016). "In zebrafish, we isolated ECs (GFP-positive, 2.2% of whole cell population) from Tg(flk:egfp) zebrafish endogenous glioma before active blood circulation occurs and detected the expression of IL-6, IL-8, FDF2 and SDF-1 by using quantitative RT-PCR." (PMID 26762853, 2016). "Taken together, our results demonstrated that migration and invasion of glioma cells was promoted through increased MMP14 expression regulated by the secretion of IL-6 from astrocytes." (PMID 27613828, 2016). "The GFP-LC3B puncta-formation assay showed that the MIR155-3p mimics further enhanced glioma cell autophagy under hypoxic conditions, partially rescuing the anti-autophagic effects of IL6 siRNA and the recombinant human IL6 antibody." (PMID 27163161, 2016). "Hypoxic regions were distributed around tumor vessels, and hypoxia-induced IL6 triggered autophagy in hypoxic glioma cells through the p-STAT3-MIR155-3p pathway." (PMID 27163161, 2016). "IL-1β promotes the self-renewal and oncogenic ability of gliomas, while IL-6 and IL-8 activate oncogenic ability of breast and colon CSCs." (PMID 26824417, 2016). "As IL6 can be derived from many sources, including glioma cells and macrophages, we double stained these markers and found that the IL6 was primarily secreted from tumor cells, with only 25% of the total amount of IL6 being secreted by nontumor immune cells." (PMID 27163161, 2016). "IL6 and p-STAT3 levels correlated with the abundance of autophagic cells and HIF1A levels in human glioma tissues and with the grade of human glioma, whereas inhibition of exogenous or endogenous IL6 repressed autophagy in glioblastoma cells in vitro." (PMID 27163161, 2016). "As shown by HE staining, the U251 xenografts grew in a more compact manner and were more homogeneous compared with glioma specimens; however, IL6, STAT3 and p-STAT3, LC3B, and HIF1A staining was essentially similar." (PMID 27163161, 2016). "Taken together, our results indicated that cytomembrane MMP14 was induced by IL-6 secreted from astrocytes, thereby enhancing the migration and invasion of glioma cells through activation of MMP2." (PMID 27613828, 2016). "This type of crosstalk between autophagy and apoptosis provides a possible avenue for interference via hypoxia-induced autophagy of glioma cells through anti-IL6 adjuvant therapy in the treatment of glioma patients." (PMID 27163161, 2016). "In contrast, M2 GAMs deteriorate this microenvironment by releasing IL6,117 which also stimulates glioma growth, neovascularization, and invasiveness." (PMID 27163161, 2016).
glioma (continued). "Our results suggest potential uses for anti-IL6 therapeutic strategies in adjuvant therapy for glioma patients." (PMID 27163161, 2016). "The results indicated that astrocytes enhanced the migration and invasion potential of glioma, possibly through the secretion of IL-6 and increased MMP14." (PMID 27613828, 2016). "The relationship between astrocytes and glioma cells was further dissected through the identification of IL-6 from protein arrays as a critical cytokine mediating an increase in cytomembrane MMP14." (PMID 27613828, 2016). "In order to further confirm a role for IL-6 in MMP14 up-regulation, IL-6 antibodies were used to block function in glioma cells in culture." (PMID 27613828, 2016). "We investigated the ability of tocilizumab to block this pathway at the source, and our positive results suggest potential uses of this drug for glioma patients in anti-IL6 therapeutic strategies, such as adjuvant therapy combined with TMZ." (PMID 27163161, 2016). "Both total protein and the cytomembrane form of MMP14 were increased in glioma cells stimulated with IL-6." (PMID 27613828, 2016). "Glioma cells were therefore directly stimulated with IL-6 (50 ng/mL) to examine its role in MMP14 expression." (PMID 27613828, 2016). "In conclusion, it is tempting to postulate that the hypoxia-IL6-p-STAT3-MIR155-3p-CREBRF-CREB3-ATG5 pathway plays a pivotal role in hypoxia-induced autophagy in glioma cells." (PMID 27163161, 2016). "In the present study, we discovered a novel anti-autophagy therapeutic strategy by targeting hypoxia-induced IL6 in glioma cells." (PMID 27163161, 2016). "Overall, our results clearly indicate that at least IL-8 induction by IL-17 in gliomas is mediated via IL-6/STAT3 axis." (PMID 26755664, 2016). "Nevertheless, similar to our previous demonstrations of high IL6 expression levels in gliomas and many other tumors, we found in the current study that IL6 also plays a role in hypoxia-induced autophagy." (PMID 27163161, 2016). "IL-6 has been reported to enhance tumor (including gliomas) migration and invasion through up-regulation or activation of MMP2 or MMP9." (PMID 27613828, 2016). "This study also demonstrates an important positive feedback regulation of the IL-6-RTVP-1 pathway that promotes glioma cell migration, GSC stemness and the mesenchymal transformation of GBM." (PMID 26267319, 2015). "Glioma cells secrete factors such as IL-10, IL-4, IL-6, M-CSF, TGF-β, and prostaglandin E2 that suppress the immune functions of microglia when these cells are located inside the tumor." (PMID 26149494, 2015). "To further analyze the regulation of RTVP-1 expression in glioma cells we employed IL-6 which phosphorylates and activates STAT3." (PMID 26267319, 2015). "We found that silencing of IL-6 reduced the mesenchymal phenotype of glioma cells and GSCs, whereas treatment of the cells with IL-6 induced an opposite effect." (PMID 26267319, 2015). "More interestingly, silencing of IL-6 abrogated the effects of RTVP-1 on glioma cell migration and on the expression of the mesenchymal markers fibronectin and α-SMA." (PMID 26267319, 2015). "Based on our GSEA and STRING analyses, we first focused on the role of IL-6 in the effects of RTVP-1 on the mesenchymal transformation of glioma cells." (PMID 26267319, 2015). "Other chemokines and cytokines known to be involved in glioma progression, such as CCL2, CXCL10 and IL-6, are selectively upregulated in the glioma-bearing hemisphere, and these increases are strongly reduced in EE mice." (PMID 25818172, 2015). "We found that similarly to RTVP-1, the expression of IL-6 correlated with the degree of malignancy of gliomas and that high IL-6 expression in GBM predicted poor prognosis." (PMID 26267319, 2015). "Treatment of A172 glioma cells with IL-6 upregulated the expression of RTVP-1 in glioma cells and the activity of the RTVP-1 promoter." (PMID 26267319, 2015).
glioma (continued). "Our data indicate that hBMVEC-secreted cytokines IL-1β and IL-6 activate sCp gene expression in C6 glioma cells." (PMID 25311416, 2014). "Of note is that the abundance of hBMVEC IL-6 and IL-1β transcripts were increased by co-culture in transwell with C6 glioma cells (respectively)." (PMID 25311416, 2014). "TNF-α has been recently demonstrated to induce IL-6 expression via STAT3 pathway in C6 glioma cells." (PMID 25275372, 2014). "As shown, the IL-6 inhibitor SC144 blocked the action of LPS-induced hBMVEC on C6 glioma cell sCp gene expression, while the IL-1β inhibitor IRAP had no notable effect." (PMID 25311416, 2014). "First, we confirmed by western blot that IL-1β and IL-6 incubated with C6 glioma cells for 6 h yielded an increase in the secretion of sCp from C6 glioma cells into the media." (PMID 25311416, 2014). "We provide evidence that human BMVEC (hBMVEC) IL-1β and IL-6 positively influence the expression of sCp transcript by neighboring C6 glioma cells (astrocytes)." (PMID 25311416, 2014). "We used IL-6 treatment at late time points post-infection to induce reactivation of HCMV gene expression in long-term infected glioma cells." (PMID 25549333, 2014). "GFAP immunoreactivity also confirmed that C6 glioma cells were differentiated into astrocytes successfully by IL-6 treatment." (PMID 23451161, 2013). "Another role in the production of MMP-9 in glioma cells is played by protein kinase C (PKC) and IL-6 is a confirmed growth factor for glioma stem cells, too." (PMID 24023566, 2013). "In this study, we investigated the role of NDRG2 in cellular apoptosis induced by oxygen-glucose deprivation (OGD) in IL-6-differentiated C6 glioma cells." (PMID 23451161, 2013). "In the present study, we found that IL-6 high expression in gliomas was significantly correlated with low expression of Cygb, as well as higher histological grade and increased neovascularization in tumors." (PMID 23688241, 2013). "In contrast cytokines IFN-α, TNF-α,IL-12p70, IL-1β, IL-6, IL-8 and IL-10, as well as metalloproteinases -2 and -9 were present in equalamounts in glioma C6 and astrocyte CMs." (PMID 23637756, 2013). "STAT3 activation in glioma TAMs is induced by many mediators known to compose the local tumor microenvironment such as IL-10, IL-6, EGF, and FGF." (PMID 23737783, 2013). "To investigate the role of NDRG2 in astrocytes, we employed the IL-6-differentiated C6 glioma cells as normal astrocytes." (PMID 23451161, 2013). "In the present study, we employed IL-6-differentiated C6 glioma cells as mature astrocytes and injured them in an OGD model, as referred previously." (PMID 23451161, 2013). "It has been shown that glioma patients have elevated levels of inflammation serum markers such as IL-6, TNF-α, and reactive protein C." (PMID 23533307, 2013). "Microglial cells recruited by glioma can promote tumor growth, dictated by paracrine loops responsible for glioma initiation and progression (e.g., IL-6, IL-10, TGF-β, prostaglandins, G-CSF, and GM-CSF, and growth factors such as EGF, VEGF, HGF, and SCF)." (PMID 22319429, 2012). "In the present study, the time- and dose-dependent stimulation of IL-6 expression by OSM was characterized in human U343 glioma cells." (PMID 21801384, 2011). "We previously reported that IL-1β significantly induces IL-6 mRNA expression and stimulates IL-6 release in C6 glioma cells." (PMID 21682888, 2011). "The observed effect of compounds HAK-2 and HAK-5 on LPS stimulation was similar to that of OSM-induced IL-6 expression in human U343 glioma cells." (PMID 21801384, 2011). "In the present study, we find that midazolam significantly suppresses IL-1β-induced IL-6 release from C6 glioma cells." (PMID 21682888, 2011). "In conclusion, our findings strongly suggest that midazolam inhibits IL-1β-induced IL-6 release in rat C6 glioma cells via suppression of STAT3 activation." (PMID 21682888, 2011).